LINC-ROR (long independently transcribed non-coding RNA, regulator of reprogramming)
Synonyms: lincRNA-RoR; lincRNA-ST8SIA3; ROR
Gene: Long non-coding RNA gene on chromosome 18 (57,054,558 to 57,072,119, reverse strand). Ensembl gene ENSG00000258609.
Diseases named in the same sentence as LINC-ROR in open-access papers:
LINC-ROR is named in the same sentence as 76 diseases in open-access papers, as found by Europe PMC text mining. Sharing a sentence is not in itself a finding about the gene and the disease. The quoted sentences say what the papers report.
breast carcinoma (48 papers, 2014 to 2025). "Previous research has shown that high levels of Linc‐ROR can cause breast cancer resistance to 5‐FU and PTX by promoting the EMT of tumour cells." (PMID 37837401, 2023). "In many breast cancer cell lines and tissues, linc-ROR is dramatically upregulated and has been implicated to contribute to malignancy and treatment resistance of advanced breast cancer." (PMID 30250400, 2018). "Our studies have suggested that linc-ROR, a critical factor for embryonic stem cell maintenance, probably acts as an oncogenic factor in breast cancer cells, causing poor prognostic outcomes." (PMID 30250400, 2018). "The study also revealed that linc-ROR acts as a competing endogenous RNA (ceRNA), modulating miR-205 activity to prevent the degradation of its target genes, which otherwise suppress breast cancer lung metastasis." (PMID 39997609, 2025). "Despite these insights, additional studies are needed to confirm the genome-wide linc-ROR occupancy profile and investigate other epigenetic markers targeted by linc-ROR in breast cancer metastasis." (PMID 39997609, 2025). "Linc-ROR inhibits BRCA1 expression, promoting a mesenchymal phenotype and increasing breast cancer metastasis risk." (PMID 39997609, 2025). "A study by Mondal and Meeran demonstrated that linc-ROR knockdown in breast cancer cells inhibited breast cancer-lung metastasis in vivo in immunodeficient mice." (PMID 39997609, 2025). "Surprisingly, linc-ROR also uniquely regulates breast cancer metastasis and epithelial–mesenchymal transitions (EMTs)." (PMID 39997609, 2025). "Secondly, linc-ROR promoted breast cancer cell migration and invasion in vitro and tumorigenesis and metastasis in vivo." (PMID 39408810, 2024). "In this regard, a breast cancer study demonstrated that linc-ROR overexpression increased stem property and EMT process by exerting a positive correlation in the Wnt/β-catenin pathway." (PMID 36827545, 2023). "In breast cancer, linc-ROR expression both in plasma and in tumor tissues was positively correlated to lymph node metastasis and estrogen and progesterone receptors, while similar results were obtained in high-grade ovarian serous cancer." (PMID 36827545, 2023). "Two studies compared plasma samples by qRT-PCR, revealing linc-ROR expression significantly higher in the plasma of breast cancer patients, a positive correlation with lymph node metastasis, and a negative relation in postoperative samples." (PMID 36827545, 2023). "The function of linc-ROR as a promoter of resistance to chemotherapeutics through various pathways in breast cancer has also been investigated." (PMID 36827545, 2023). "Linc‐ROR exhibits upregulation in human breast cancer MDA‐MB‐231 cells and exerts a negative regulatory effect on miR‐34a‐5p expression." (PMID 37837401, 2023). "In two breast cancer studies, the linc-ROR acted as a miR-205 sponge to overexpress ZEB1 and ZEB2 and decrease the expression of E-cadherin." (PMID 36827545, 2023). "Somestudies revealed that linc-ROR can act as an oncogenein breast cancer tissue and it was related to lymph nodemetastasis and worse prognosis." (PMID 34455716, 2021). "Overexpressed linc‐ROR was reported to be a potential biomarker for the diagnosis and dynamic monitoring of breast cancer, and the expression levels of linc‐ROR are significantly higher in breast cancer tissues and plasma than in controls." (PMID 32335998, 2020). "Through correlation analysis, we found that the expression of miR‐194‐3p was negatively correlated with the expression of linc‐ROR in breast cancer tissues." (PMID 32335998, 2020).
breast carcinoma (continued). "First, we determined the proliferation status of these cell lines and found that the overexpression of miR‐194‐3p inhibited the proliferation of the breast cancer cells and reduced the promoting effect of linc‐ROR on proliferation." (PMID 32335998, 2020). "Since the overexpression of linc‐ROR was found to decrease the sensitivity of breast cancer cells to rapamycin, the miR‐194‐3p mimic or NC mimic was transfected into MCF‐7 cells and LV‐linc‐ROR cells to explore the underlying regulatory mechanism." (PMID 32335998, 2020). "Cell proliferation assay was performed to examine the role of linc‐ROR in breast cancer cell proliferation." (PMID 32335998, 2020). "According to RT–qPCR validation, miR‐194‐3p was significantly downregulated in the linc‐ROR‐overexpressing cell line (LV‐linc‐ROR) and significantly downregulated in the breast cancer tissues that expressed high levels of linc‐ROR." (PMID 32335998, 2020). "In our study, linc‐ROR was found to be upregulated in breast cancer tissues compared with paracarcinoma tissues, indicating its carcinogenic potential." (PMID 32335998, 2020). "Then, transwell assays indicated that the overexpression of miR‐194‐3p inhibited the migration and invasion abilities of breast cancer cells, and reduced the effect of linc‐ROR on promoting these abilities." (PMID 32335998, 2020). "linc‐ROR promoted the cell proliferation, colony formation, cell migration, and invasion of breast cancer and decreased the sensitivity of breast cancer cells to rapamycin." (PMID 32335998, 2020). "Specifically, linc-ROR overexpression prevents the degradation of mir-205 target genes in breast cancer cells, including the EMT inducer ZEB2." (PMID 31214490, 2019). "Linc-ROR was knockdown in breast cancer cell lines and the effects on cell proliferation, migration and invasion were tested both in vitro and in vivo tumor model." (PMID 30250400, 2018). "Our data suggest that linc-ROR, in combination with other lncRNAs associated with breast cancer, may serve as a clinically beneficial biomarker for detecting neoplastic cells, differentiating the different stages of breast cancer and predicting prognostic outcomes." (PMID 30250400, 2018). "We compared the expression levels of linc-ROR in cells cultured in vitro and found that the expression in two breast cancer cell lines (MCF-7 and MDA-MB-231) were higher than that in the normal mammary fibroblast cell line (Hs578Bst)." (PMID 30250400, 2018). "The effect of the Linc-ROR on epithelial-to-mesenchymal transition was verified to contribute to the chemotherapy resistance and invasion of breast cancer cells." (PMID 29549263, 2018). "We tried to further assess the expression of linc-ROR in clinical prognosis of breast cancer patients." (PMID 30250400, 2018). "Our study has confirmed aberrant overexpression of linc-ROR in both breast cancer cell lines and patient tumors, demonstrating its strong correlation with poor prognostic outcomes." (PMID 30250400, 2018). "Further characterization suggested the role of linc-ROR in enhancing proliferation and invasion of breast cancer cells as well as promoting tumor growth in nude mice." (PMID 30250400, 2018).
breast carcinoma (continued). "Recent research suggested that Linc-ROR functions as an onco-lncRNA to promote estrogen-independent growth of ER+ breast cancer by the MAPK/ERK signaling pathway." (PMID 29549263, 2018). "The results have highlighted the potential importance of linc-ROR in the progression of advanced breast cancer, and thus will stimulate efforts in the development of novel diagnostic and therapeutic strategies." (PMID 30250400, 2018). "In the same year, One study concluded that Linc-ROR suppressed gemcitabine-induced autophagy and apoptosis in breast cancer cells by silencing miR-34a expression." (PMID 29549263, 2018). "In summary, our results highlight the novel functional impact of linc-RoR in promoting estrogen-independent growth of ER+ breast cancer." (PMID 29041978, 2017). "Overexpression of linc-ROR promotes metastasis of breast cancer cells in vivo while linc-ROR knockdown hindered metastasis." (PMID 28430163, 2017). "The present study demonstrates that linc-RoR functions as a modulator to promote estrogen-independent growth and tamoxifen resistance of breast cancer cells." (PMID 29041978, 2017). "We identified that linc-RoR functions as an onco-lncRNA to promote estrogen-independent growth of ER+ breast cancer." (PMID 29041978, 2017). "Linc-ROR is reported to stimulate EMT process by acting as a ceRNA for miR-205 in breast cancer cells." (PMID 28388536, 2017). "Reports have been confirmed that elevated linc-ROR contributes to the oncogenesis and development of many types of cancers including hepatocellular cancer, breast cancer and endometrial cancer." (PMID 28388536, 2017). "Ectopic overexpression of linc-ROR enhanced breast cancer cell migration and invasion, whereas silencing repressed tumor growth and lung metastasis in vivo." (PMID 27686732, 2016). "More recently, linc-ROR has been demonstrated to play an important role in the regulation of breast cancer metastasis and EMT CSCs." (PMID 26932376, 2014). "Estrogen receptor positive (ER+) breast cancer cell lines were utilized to knock out linc-ROR expression through CRISPR/Cas9 technology, revealing that linc-ROR functions as an onco-lncRNA to promote growth through activation of the MAPK/ERK pathway by regulating ERK-specific phosphatase DUSP7." (PMID 36827545, 2023). "Moreover, linc-ROR inhibition reversed resistance to tamoxifen by inducing autophagy in the breast cancer cell line BT474." (PMID 36827545, 2023). "However, in breast cancer, linc-ROR, which has a high expression level in breast cancer tissues and plasma, can act as a competitive endogenous RNA (ceRNA) for miR-194-3p." (PMID 37345019, 2023). "LincRNA‐regulator of reprogramming (Linc‐RoR), a regulator that promotes oestrogen‐independent breast cancer cell growth and tamoxifen resistance, plays an essential role in endocrine therapy resistance of breast cancer." (PMID 34651424, 2021). "The overexpression of miR‐194‐3p increased the sensitivity of breast cancer cells to rapamycin, thus reducing cell viability in the presence of rapamycin, and the rescued miR‐194‐3p expression reduced the linc‐ROR‐mediated decrease in the sensitivity of breast cancer cells to rapamycin." (PMID 32335998, 2020). "The overexpression of linc‐ROR triggered changes in the whole transcriptome of breast cancer cells, and a total of 85 lncRNAs, 414 microRNAs, 490 mRNAs, and 92 circRNAs were differentially expressed in the linc‐ROR‐overexpressing cell line compared with the negative control." (PMID 32335998, 2020). "The results from both sides suggested that linc‐ROR could promote cell migration and invasion in breast cancer." (PMID 32335998, 2020).
breast carcinoma (continued). "Also, our data indicated that linc-ROR functioned as a ceRNA to regulate mir-205 activity to prevent the mir-205 target genes from degradation, leading to breast cancer lung metastasis." (PMID 32929060, 2020). "The target genes of these DE‐RNAs were subjected to GO and KEGG pathway analyses, and the results revealed the possibility that linc‐ROR may affect the development and progression of breast cancer through a ceRNA mechanism." (PMID 32335998, 2020). "linc‐ROR is an important marker for multidrug resistance in breast cancer, and its upregulation is important for chemotherapy tolerance, and it confers the resistance of breast cancer cells to gemcitabine by silencing miR‐34a expression." (PMID 32335998, 2020). "However, further studies are required to validate the genome-wide profile of linc-ROR occupancy for exploring more linc-ROR-targeting epigenetic marks in breast cancer metastasis." (PMID 32929060, 2020). "linc‐ROR (long intergenic non‐protein‐coding RNA, regulator of reprogramming) is a kind of intergenic noncoding RNA that has been shown to be dysregulated in many types of cancers, including breast cancer." (PMID 32335998, 2020). "We found that linc‐ROR functioned as an onco‐lncRNA in breast cancer." (PMID 32335998, 2020). "The plate colony formation assay also suggested that LV‐linc‐ROR promoted the colony formation of breast cancer cells and that si‐linc‐ROR suppressed it; these results were obtained either by directly observing the colony after staining or by counting the number of colonies." (PMID 32335998, 2020). "This reinforced our hypothesis that linc-ROR may be an oncogenic factor for the development of breast cancer." (PMID 30250400, 2018). "In order to understand how linc-ROR may support the development of breast cancer, we analyzed its impact on TGF-β, a critical signaling factor orchestrating mammary epithelial development and contributing to cancer progression in the advanced stages." (PMID 30250400, 2018). "We found that linc-ROR was overexpressed in both breast cancer cell lines and patient tissues." (PMID 30250400, 2018). "Our results have further suggested that the TGF-β signaling pathway may be a downstream target of linc-ROR, responsible for promoting breast cancer." (PMID 30250400, 2018). "Therefore, linc-RoR was selected for further characterization of its role in estrogen-independent growth and tamoxifen resistance of breast cancer." (PMID 29041978, 2017). "LINC-ROR knockdown through in vitro and in vivo experiments indicated that this lncRNA may also contribute to cancer progression, since its inhibition reduces cell proliferation, invasion and migration, while LINC-ROR knockout enhanced breast cancer cell sensitivity to tamoxifen." (PMID 34359587, 2021). "By upregulating and downregulating the expression level of linc‐ROR in breast cancer cell lines, we found that the overexpression of linc‐ROR could promote cell proliferation, colony formation, and cell migration, and invasion, while reducing expression had the opposite effects." (PMID 32335998, 2020). "That is, linc‐ROR could downregulate the expression of miR‐194‐3p in breast cancer." (PMID 32335998, 2020). "For example, linc‐ROR could promote chemotherapy tolerance of breast cancer, regulate gemcitabine resistance in breast cancer, regulate chemoresistance in docetaxel‐resistant lung adenocarcinoma cells, and contribute to the resistance of pancreatic cancer cells to gemcitabine." (PMID 32335998, 2020). "The results suggested that high expression of linc-ROR might be important in breast cancer." (PMID 30250400, 2018).